CCNB1 (cyclin B1)
Diseases named in the same sentence as CCNB1 in open-access papers (continued):
Sharing a sentence is not in itself a finding about the gene and the disease.
tumor (continued). "Tumours collected from mice at diestrus exhibited a significant increase in the expression of genes Mki67 (p = 0.05), Ccnb1 (p = 0.02), Erbb2 (p = 0.03), Grb7 (p = 0.02), and Bag1 (p = 0.05), compared to tumours collected at estrus." (PMID 34174867, 2021). "Compared with EXOvector, the administration of EXOcirc_0001610 resulted in increased tumor volume and weight, a lower miR-139-5p level, and higher protein levels of cyclin B1 and Ki-67 in the tumors of nude mice injected with EC cells." (PMID 34462422, 2021). "Western blot analyses from infigratinib‐resistant tumour collected at different passages indicated an elevation in cell cycle proteins such as cyclin E2, cyclin B1, Cdc25C, p‐Cdc2, cyclin D1, Rb and p‐Rb." (PMID 33179425, 2021). "As observed in ELF3 knockdown or ANF treatment in vitro experiments in A549 and H1975 cells, cyclin A2, cyclin B1, and cyclin D1 were reduced in xenograft tumor tissues treated with ANF/GEF combination." (PMID 34830169, 2021). "IHC showed that circSLC7A11 knockdown attenuated the expression of CDK1, cyclin B1, and N-cadherin, but enhanced that of E-cadherin in xenograft tumor tissues, consistent with the in vitro results." (PMID 34844614, 2021). "The expression of CCNA2 and CCNB1 was also positively correlated with tumor-killing immune cells, such as CD8+ T cells." (PMID 33996604, 2021). "Specific cyclin genes such as Ccna2, Ccnb1, Ccnb2, and Ccne1 encoding CYCLIN A2, B1, B2, and E1, respectively, were also upregulated in MMTV-R26Met tumours." (PMID 34646365, 2021). "An in vivo xenograft experiment showed that the ectopic expression of circ-Ccnb1 significantly repressed tumor growth." (PMID 32204575, 2020). "Meanwhile, through the analysis of DEG expression in the GEO database, CCNB1 was also highly expressed in tumor tissues (log FC = 1.51, p = 2.41E-37)." (PMID 33628185, 2020). "Cyclin B1 overexpression shortens cell cycle length and allows tumor cells to bypass checkpoint control, leading to uncontrolled proliferation." (PMID 31906456, 2020). "Positive scores in ≥1 tumor area were observed for 94 (38%) patients for CCNB1 and 103 (42%) patients for PTTG1." (PMID 31801961, 2020). "Collectively, these results indicate that GSK3β-mediated regulation of cell cycle progression via cyclin D1, CDK4 and cyclin B1 is responsible for tumor cell survival and proliferation in ESCC." (PMID 32678196, 2020). "The high expression level of cyclin B1 is also correlated to the degree of tumor invasion and metastasis." (PMID 32219041, 2020). "CCNB1 is significantly correlated with the degree of tumor infiltration, aggressiveness, and adverse clinical outcome of the patients." (PMID 33628185, 2020). "BITC induced G2 arrest and apoptosis, decreasing tumor growth in nude mice by downregulation of cyclin B1 and Cdk1 expression." (PMID 33263014, 2020). "As a transcription factor, FOXM1 crosstalk with multiple proteins including PLK1, Cyclin B1 and Aurora B, and thus plays a central role in tumor aggressiveness." (PMID 32047721, 2020). "Proliferation, measured by Cyclin B1 labeling index, was unchanged in the muscle‐invasive progression tumor." (PMID 31609466, 2020). "The down-regulation of cyclin B1 results in tumor regression, making CCNB1 an attractive target for further study." (PMID 32219041, 2020). "HuR contributes to tumor proliferation by modulating mRNAs of cell cycle-related genes, such as those for Cyclin A, Cyclin B1, and Cyclin E1." (PMID 32967226, 2020). "BITC was found to induce apoptosis to suppress tumor growth in nude mice by downregulating cyclin B1 and Cdk1 expression." (PMID 33263014, 2020).
tumor (continued). "Consistent with the in vitro results, apoptosis (cleaved-caspase-3 staining) and CCNB1 of the tumor specimens increased significantly, whereas CCNB1 of the tumor specimens decreased significantly in the C3G group." (PMID 31696058, 2019). "There was increased expression of pro-proliferative and tumor promoting genes such as Ccnb1, Ccnd1, Survivin, and Myc, while the expression of Cdkn1a, an inhibitor of cell cycle progression, was significantly reduced in Nlrp12-/- HCC." (PMID 30990169, 2019). "CCNB1 expression was related with years (P = 0.018) and tumour location (P = 0.036) in RMS patients." (PMID 31870357, 2019). "The abnormally expressed cyclin B1 is also considered as a tumor antigen and used for early cancer detection." (PMID 31803360, 2019). "To confirm that yatein exhibited the same antitumor mechanisms in vivo as observed in vitro, we evaluated cyclin B1 expression and Cdc2 phosphorylation in the tumor tissue in the vehicle control and yatein-treated groups." (PMID 31533296, 2019). "Under certain circumstances Cyclin B1 has been regarded as an essential molecule in the determination of tumor cell fates." (PMID 31249607, 2019). "Consistent with our findings, a series of previous studies reveal that down‐regulation of Cyclin D1 or Cyclin B1 can be induced significantly less colony‐forming, stronger anti‐proliferative effect, and pro‐apoptosis ability in different tumor cell lines." (PMID 31173492, 2019). "The CCNB1 gene is overexpressed in many human tumours and is involved in the proliferation, invasion, metastasis and recurrence of various tumours." (PMID 31585531, 2019). "The results showed that CCNB1 silencing significantly reduced the xenograft tumour volume (p < 0.0001) and weight (p < 0.001) in vivo." (PMID 31585531, 2019). "In vivo experiments of subcutaneous tumor formation further demonstrated that miR-144 suppressed tumor formation by negative regulation of CCNB1." (PMID 30651720, 2019). "Real-time PCR showed that the tumor tissues from circ-Ccnb1-transfected cells expressed higher levels of circ-Ccnb1 relative to control (right)." (PMID 29795334, 2018). "These experiments showed that survival of Brca1-mutant tumor cells decreased with each increment in cyclin B1 induced by successively higher concentrations of vinblastine." (PMID 30327455, 2018). "After 20 days of treatment, massive enlargement of tumor volume for both control groups (1300 mm3 and 1100 mm3) were seen in contrast to cyclin-B1-ssiRNA/PEI group (700 mm3)." (PMID 29861465, 2018). "For example, PBK/TOPK is upregulated during the cytogenesis of tumor cells, most likely by phosphorylation of Thr9 and activation by cyclin B1/cdk1." (PMID 30286126, 2018). "In conclusion, Cyclin-B1 has a prominent role in tumor cell proliferation and is found to be heterogeneously expressed in multiple cancers." (PMID 29861465, 2018). "Previous studies revealed that CCNB1 promotes cell proliferation, tumor growth, and cancer recurrence and relates to progression and survival in various cancers." (PMID 30363964, 2018). "To examine this directly, we analyzed tumor sections by in situ hybridization and confirmed the presence of high levels of circ-Ccnb1 in both groups of tumors, reaching a p-value of significance." (PMID 29795334, 2018). "Correlative analysis revealed that, in men, CTAG2 expression was strongly correlated with known lactotroph tumor aggressiveness markers implicated in the cell cycle (CENPE, AURKB, CCNB1, ADAMTS6)." (PMID 30555413, 2018). "The notable antitumor efficacy of Cyclin-B1-siRNA for both intravenous and Intratumoral administration and their prolonged survival rate confer new prospective for tumor management modality." (PMID 29861465, 2018).
tumor (continued). "The ssiRNA cyclin-B1-PEI complex delivered the cyclin-B1-ssiRNA to the targeted tumor cell and down regulated the Cyclin-B1 expression which resulted in significant inhibition of tumor growth." (PMID 29861465, 2018). "Sticky siRNA (ssiRNA) targeting Cyclin-B1 exerted 44% reduction in tumor volume and improved biological safety profile in malignant melanoma." (PMID 29861465, 2018). "Our data also confirmed that CPT-induced G2/M phase arrest was accompanied by p21 and cyclin B1 expression, which functions as a tumor suppressor and initiates cell cycle arrest by inhibiting Cdk activity in G2/M phase in response to DNA damage." (PMID 29774099, 2018). "Analysis of tumor masses showed that significant up-regulation of circ-Ccnb1 was detected not only in the tumors formed by circ-Ccnb1-transfected cells, but also in the tumors where circ-Ccnb1 expression plasmids were injected (right)." (PMID 29795334, 2018). "Cyclin B1, as a tumor antigen, is a key mitotic cyclin in the G2/M phase transition of the cell cycle." (PMID 29899555, 2018). "Other examples in which overexpression of a mitotic regulator is accompanied of CIN and tumor formation include Aurora A48,49, Aurora B8, and Cyclin B1 and Cyclin B27, among others." (PMID 30069007, 2018). "In line with the observed cell cycle deceleration, cell cycle proteins Cyclin B1 and D1 that are often overexpressed in tumor cells were downregulated upon SATB1 knockdown." (PMID 28049521, 2017). "Cyclin B1, encoded by the CCNB1 gene, has been demonstrated to play a pivotal role in tumorigenesis and tumor development." (PMID 27903976, 2017). "Since VPA possesses an anti-cancer effect to influence tumor cell proliferation and apoptosis, its effect on several additional proliferation and apoptotic-related molecules, such as cyclin B1, cdc2, p21, Bcl-xL, and Bim were investigated." (PMID 28108734, 2017). "Tumor tissues derived from shPRC1–1 transduced cells exhibited reduced positivity for Ki67, Cyclin B1 and Cdc2 compared with the control groups." (PMID 28646916, 2017). "In our research, the results suggest that 17-DMAG induces accumulation of cyclin B1 and inhibits tumor cell proliferation." (PMID 26786409, 2016). "Dinaciclib significantly inhibited the cyclinT1, CDK9, c-MYC, cyclin B1 and survivin protein expression levels in tumor tissues (n=3)." (PMID 27486754, 2016). "Tumor and non-tumor samples differed significantly in the expression of 10/22 genes: CCNB1, CLDN4, CLDN6, MMP2, MUC1 (all: p < 0.05), BAG1, SERPINB3 (all: p < 0.01), CD44 (standard variant), MKI67, and MYBL2 (all: p < 0.001)." (PMID 27542596, 2016). "We demonstrated that inhibition of CDK1 or cyclin B1 by RNAi to reduced tumor cell proliferation in TNBC." (PMID 27486754, 2016). "Equally important, analysis of IHC staining for P-Smad2, p27 and Cyclin B1 in tumor sections confirmed the in vitro results." (PMID 26460952, 2015). "As expected, there was a down regulation of cellular proliferation molecules CDK1, CDK2, CDK4, CDK6, Cyclin D1, Cyclin E and Cyclin B1 and upregulation of p16 and p21 in the xenograft tumor tissues by IHC." (PMID 26590805, 2015). "High cytoplasmic level of CDK1Tyr15 and pCDK1Thr161 and high expression of Cyclin B1 (total) in either cytoplasm or nucleus were correlated with large tumor diameter, poor histological differentiation and deep invasion." (PMID 25849598, 2015).
tumor (continued). "An increasing body of data suggests that altered expression of cyclin B1 is a frequent event in tumor cells." (PMID 25978027, 2015). "Elevated levels of CDK1Tyr15, pCDK1Thr161, Cyclin B1 (total) and pCyclin B1Ser126 were correlated with advanced tumor behaviors and aggressive features." (PMID 25849598, 2015). "Cdk1 as well as CCNB1 expression were readily detectable in all embryonal tumor cell lines investigated." (PMID 26029996, 2015). "When tumor cells invade into surrounding tissues and further metastasize into distant tissues, the expression of Cyclin B1 is decreased and negatively correlated with poor survival." (PMID 25962181, 2015). "6-OAP treatment did not perturb Skp1 expression, but down-regulated NIPA and Skp2, and up-regulated Cyclin B1 and E-cadherin in tumor samples." (PMID 26474281, 2015). "Nevertheless, both cdk1 expression and CCNB1 expression were significantly higher in MYCN-amplified tumor." (PMID 26029996, 2015). "In at least 25% of tumor cases high expression of CDK1Tyr15, pCDK1Thr161, Cyclin B1 (total) and pCyclin B1Ser126 was observed, compared to the low levels in normal vulvar squamous epithelium." (PMID 25849598, 2015). "Decreased prostate carcinogenesis in SPDEF-deficient mice was associated with decreased proliferation of tumor cells and reduced expression of Cdc25b, Cyclin B1, Plk-1, AuroraB, and Topo2alpha, factors that are critical for tumor cell proliferation." (PMID 25254494, 2014). "We observed that CXCR7 depletion increased p21 and decreased Cyclin B1 accumulation, thus preventing the tumor cells from dividing." (PMID 25168820, 2014). "In order to validate this new technology, we chose to design sticky siRNAs against two well-known players of the tumor progression process, survivin and cyclin B1." (PMID 23835136, 2013). "Topical caffeine increased the percentage of mitotic tumor cells with cyclin B1 by 70%, and the percentage of mitotic keratoacanthoma and squamous cell carcinoma cells with caspase 3 (active form) was increased by 214 and 317%, respectively." (PMID 23785666, 2013). "The results presented in this work demonstrate that PEI-mediated systemic delivery of sticky siRNAs against survivin and cyclin B1 lead to an efficient inhibition of tumor growth." (PMID 23835136, 2013). "Our study findings draw attention to cyclin B1 overexpressions involvement in early carcinogenesis, cell differentiation and tumor proliferation." (PMID 23722120, 2013). "Researchers are investigating the potential of depleting Cyclin B1 expression in tumours as a therapeutic strategy, by initiating anti-proliferative and apoptosis-inducing properties." (PMID 23874748, 2013). "This same unusual enrichment of cyclin B1 was found in polyploid tumour cells induced by irradiation, in parallel with the Aurora B-kinase enrichment." (PMID 24025698, 2013). "The WDSCC showed nuclear staining of cyclin B1 in peripheral layers of cells, in tumor islands as well as in sheets." (PMID 23722120, 2013). "The concomitant increase in cyclin B1 overexpression from VC to grades COSCC was observed.Conclusion: Our study findings draw attention to cyclin B1 overexpression is involved in early carcinogenesis, cell differentiation and tumor proliferation." (PMID 23722120, 2013). "Our studies revealed that cyclin B1 and Aurora B kinase overexpressed in endopolyploid tumour cells are important regulators of the transition from the normal mitotic cycle to tetraploidy." (PMID 24025698, 2013). "We performed Western blotting analysis on molecules whose expressions were changed in relatively a large number of tumor tissues, including cyclin B1, caveolin 1, collagen VI, ACC1/pS79, CHK2, and IGFBP2." (PMID 22348039, 2012). "A number of biomarkers identified here are consistent with those reported in the literature in terms of their altered gene expressions in tumor tissues, including caveolin 1, cyclin B1, 14-3-3zeta, Stat5, activated p38, and IGFBP2." (PMID 22348039, 2012).
tumor (continued). "Expression of cyclin B1 was significantly higher in poorly differentiated tumor tissues than in moderately or well-differentiated tumor tissues (p<0.025)." (PMID 22348039, 2012). "Our data showed that although expression of cdk-4, cdk-6, and p27 was not affected by sorafenib, the levels of cyclin D1, cyclin cdk-2, and cyclin B1 in sorafenib-treated tumours were significantly reduced as compared with controls (P<0.05)." (PMID 21407223, 2011). "Taken together, the CSR SP and CCNB1 GSA-Tumor analyses are consistent with results from meta-analyses of different prognostic gene signatures, including CSR, identifying proliferation as the major constituent of several signatures." (PMID 21445301, 2011). "Using GSA-Tumor we stratified the 1881-tumor set into three quantiles based on CCNB1 gene expression." (PMID 21445301, 2011). "Elevated cyclin B1 expression often precedes tumour immortalization and aneuploidy suggesting that deregulated expression of cyclin B1 is an early tumorigenic event." (PMID 20846384, 2010). "Aberrant activity of cyclin B1/Cdk1 is found in the radiation-derived tumor resistance, and inhibition of cyclin B1/Cdk1 activity enhances tumor radiosensitivity by increasing apoptosis." (PMID 20808790, 2010). "Tumours with the highest cyclin B1 expression (>10%) were more frequent among BRCA1 than sporadic (OR 2.8, 95% CI 1.4–5.6, P=0.003) or familial BRCA1/2 mutation negative (OR 4.8, 95% CI 2.3–9.9, P<0.0005) patients." (PMID 19293801, 2009). "The conditional deletion of Foxm1 from lung epithelial cells strikingly decreased the development of lung tumors in mice, diminished proliferation of tumor cells and reduced the expression of cyclin B1 and TOPO-2α." (PMID 19672312, 2009). "The correlations between cyclin B1 and other tumour features show that high cyclin B1 expression is common among tumours with an aggressive phenotype." (PMID 19293801, 2009). "Cyclin A gene expression was increased in 9/12 tumours, cyclin B1 in 9/12 tumours, cyclin D1 in 7/12 tumours and cyclin E in all 12 tumours." (PMID 19615042, 2009). "The data suggest that cyclin B1 is indeed required in vivo for promoting proliferation of tumor cells and the reduction of cyclin B1 slows down the tumor growth." (PMID 19113992, 2008). "Taken together, deregulation of cyclin B1 is involved in neoplastic transformation and promotes proliferation of tumor cells." (PMID 19113992, 2008). "Among the significant genes that show a high expression in tumours with unfavourable outcome, cell cycle associated genes can be found (E2F1, CCNA2, CCNB1, KIFC1)." (PMID 17531100, 2007). "The CCNB1 protein level was also increased in tumor tissues (2.22-fold, p = 0.0257)." (PMID 41568058, 2026). "CCNB1 has been identified as tumor-promotor in multiple tumors." (PMID 40682115, 2025). "Furthermore, it was discovered that USP39 functions not only as a splicing factor and regulator of mRNA maturation but also as a novel deubiquitinating enzyme of Cyclin B1, thereby participating in the proliferation of tumor cells." (PMID 40990019, 2025). "These suggested that CCNB1 may play a role in mediating drug resistance, an aspect of tumor biology that warrants further investigation." (PMID 40682115, 2025). "Importantly, the combination of SNRPB overexpression and CCNB1 knockdown resulted in a partial reversal of the enhanced tumor growth induced by SNRPB overexpression." (PMID 40682115, 2025).